EZH2 (enhancer of zeste 2 polycomb repressive complex 2 subunit)
Diseases named in the same sentence as EZH2 in open-access papers (continued):
Sharing a sentence is not in itself a finding about the gene and the disease.
follicular lymphoma (continued). "In summary, circulating tumor DNA based EZH2 mutation analysis offers a rapid, real-time, radiation-free monitoring tool for sensitive detection of EZH2 mutations deriving from different anatomical sites in follicular lymphoma patients receiving immunochemotherapy." (PMID 32668764, 2020). "Here, we demonstrated on four follicular lymphoma cases that circulating tumor DNA based EZH2 mutation analysis performed by a highly sensitive droplet digital PCR method may be a valuable treatment monitoring approach in EZH2 mutant follicular lymphoma." (PMID 32668764, 2020). "Tazemetostat is a first-in-class Food and Drug Administration (FDA)–approved oral EZH2 inhibitor for follicular lymphoma and epithelioid sarcoma." (PMID 41544165, 2026). "Epigenetic dysregulation is a hallmark of Diffuse large B- cell lymphoma (DLBCL) and follicular lymphoma (FL), with gain of function (GOF) EZH2 mutations." (PMID 42211521, 2026). "Tazemetostat, the first FDA-approved EZH2 inhibitor, has demonstrated significant clinical benefits in treating epithelioid sarcoma and follicular lymphoma." (PMID 40310411, 2025). "Tazemetostat (Tazverik), an EZH2-specific small molecule inhibitor, was approved for epithelioid sarcoma and follicular lymphoma." (PMID 39934895, 2025). "Diffuse large B cell lymphomas and follicular lymphomas show recurrent mutations in epigenetic regulators; among these are loss-of-function mutations in KMT2D and gain-of-function mutations in EZH2." (PMID 40504770, 2025). "Tazemestat, an EZH2 inhibitor that has shown superior methyltransferase activity in EZH2-mutant versus wild-type Follicular Lymphoma (FL) in early clinical trials, has also been granted accelerated approval by the FDA for the treatment of R/R FL." (PMID 40600050, 2025). "Germinal center B cell subtype of DLBCL (GCB–DLBCL), as well as follicular lymphomas (FL) which are the second most common type of NHL, exhibit recurrent heterozygous somatic point mutations in EZH2." (PMID 40504770, 2025). "EZH2 mutations and BCL2 translocations are characteristic of both follicular lymphoma (FL) and DLBCL, which has transformed from FL." (PMID 40507898, 2025). "Tazemetostat, an oral EZH2 inhibitor, is the first-in-class FDA-approved agent for epithelioid sarcoma and relapsed or refractory follicular lymphoma with EZH2 mutation." (PMID 40872531, 2025). "In relapsed or refractory follicular lymphomas, the tumor response rate with tazemetostat was 34% in EZH2 wild-type diseases and 69% in EZH2 mutant diseases." (PMID 39941804, 2025). "Tazemetostat, which specifically targets EZH2, has already shown promise in clinical trials for other cancers, including follicular lymphoma and epithelioid sarcoma." (PMID 40074445, 2025). "Tazemetostat, which inhibits both Y641N-mutant and wild-type forms of EZH2, has been shown to induce cell cycle arrest and apoptosis in preclinical models of follicular lymphoma." (PMID 40805121, 2025). "Tazemetostat, the first oral enhancer of zeste homolog 2 (EZH2) inhibitor, has been approved for EZH2 mutation-positive follicular lymphoma and epithelioid sarcoma." (PMID 40450300, 2025). "Although an objective response rate of 69% was observed in the EZH2- mutant cohort of a phase 2 trial in patients with follicular lymphoma, EZH2 inhibitors have so far shown limited effectiveness in most solid tumors, particularly in the pediatric population." (PMID 39984702, 2025). "Tazemetostat (TAZ) is a selective oral EZH2 inhibitor which has US Food and Drug Administration approval in follicular lymphoma." (PMID 40166656, 2025). "Previously, we reported the efficacy and safety of tazemetostat in Japanese patients with relapsed/refractory follicular lymphoma (FL) and diffuse large B-cell lymphoma (DLBCL) harboring the EZH2 mutation in a multicenter, open-label, phase II study." (PMID 39179948, 2024).
follicular lymphoma (continued). "The most advanced clinical trials include tazemetostat, an Enhancer of zeste homolog 2 (EZH2) inhibitor approved for follicular lymphoma." (PMID 39445823, 2024). "Tazemetostat (Taze), an FDA-approved EZH2 inhibitor (EZHi), has already provided meaningful and sustained responses for relapsed or refractory follicular lymphoma patients." (PMID 38355622, 2024). "Currently, EPZ-6438 (tazemetostat) is a first-in-class U.S. FDA-approved EZH2 inhibitor for follicular lymphoma and epithelioid sarcoma." (PMID 39408226, 2024). "The other EZH2 inhibitor Tazemetostat also showed excellent results in a phase II clinical trial (NCT01897571) for the treatment of relapsed or refractory follicular lymphoma." (PMID 38644473, 2024). "The market approval of Tazemetostat (TAZVERIK) for the treatment of follicular lymphoma and epithelioid sarcoma has established “enhancer of zeste homolog 2” (EZH2) as therapeutic target in oncology." (PMID 38242973, 2024). "Using a unique longitudinal follicular lymphoma cohort, we further link EZH2 status to abnormal H3K27 methylation." (PMID 38658543, 2024). "Overall, the mutation profile of the MYC/BCL2/BCL6-TH group is very similar to that of the MYC/BCL2-DH group, characterised by frequent mutations in follicular lymphoma associated genes (BCL2, CREBBP, KMT2D, EZH2, TNFRSF14)." (PMID 38184753, 2024). "Tazverik® (tazemetostat) targets histone methyltransferase EZH2 (responsible for H3K27me2/3) and has been approved for the treatment of epithelioid sarcoma and follicular lymphoma and solid tumours." (PMID 37731322, 2023). "Personalized therapies can be used to target these alterations, for example tazemetostat, an oral EZH2-inhibitor, produces durable responses in the setting of relapsed and refractory follicular lymphoma." (PMID 37869076, 2023). "A significant study revealed a sizable cohort of EZH2 variant-positive diffuse large B-cell lymphoma (DLBCL) and follicular lymphoma cases." (PMID 37830606, 2023). "In a single-arm clinical study, tazemetostat, an oral EZH2 inhibitor, demonstrated significant therapeutic efficacy and safety in follicular lymphoma treatment, particularly in the EZH2 wild-type cohort." (PMID 38264522, 2023). "For instance, SHR2554, an EZH2 inhibitor, has shown promising antitumor activity in patients with relapsed or refractory follicular lymphoma, peripheral T-cell lymphoma, and classical Hodgkin lymphoma." (PMID 37853413, 2023). "Another inhibitor of EZH2, Tazemetostat (TAZVERIK, Epizyme, Inc.)was approved by US- FDA in June 2020 for treating adult patients with relapsed or follicular lymphoma with EZH2 positive mutations." (PMID 36092905, 2022). "In the case of targeting components of the PRC2/1 complexes to increase anticancer immunity, inhibition of EZH2 has been effective against rare sarcomas and follicular lymphomas." (PMID 35795673, 2022). "The FDA has approved the EZH2 inhibitor tazemetostat for the therapeutic indication of epithelioid sarcoma and follicular lymphoma; thus, there are safe EZH2 inhibitors available." (PMID 36142368, 2022). "Of note, the EZH2 inhibitor tazemetostat has been approved by U.S. Food and Drug Administration for the treatment of follicular lymphoma." (PMID 34980213, 2022). "Several EZH2 inhibitors, which inhibit the methyltransferase activity of EZH2, have shown promising results in treating sarcoma and follicular lymphoma in clinics." (PMID 34195095, 2021). "In B cell lymphoma, aberrancy of EZH2 has been associated with EZH2 tyrosine 641 (Y641N) mutation seen in ~22% of diffuse large B-cell lymphoma (DLBCL) and 7% of follicular lymphoma (FL) patients." (PMID 32850364, 2020). "In patients with follicular lymphoma (FL), we, as others, identified frequent mutations in KMT2D, CREBBP, and EZH2 with frequencies of 8/10, 5/10, and 4/10, respectively." (PMID 32013121, 2020).
follicular lymphoma (continued). "Recent reporting on these ongoing clinical studies indicated significant responses in EZH2 mutant patients, with as many as 92% of EZH2-mutant follicular lymphoma patients responding to treatment." (PMID 31123059, 2019). "The first-in-class EZH2 inhibitor, tazemetostat, demonstrated enhanced clinical activity in mutant follicular lymphoma, and DLBCL patients." (PMID 31403034, 2019). "Importantly, EZH2 has been largely involved in B-cell pathophysiology, as demonstrated by evidence that, in germinal centers, high EZH2 levels trigger B cell expansion, while EZH2-activating mutations may promote development of diffuse large B-cell and follicular lymphomas." (PMID 29290968, 2017). "In B-cell lymphomas, heterozygous gain-of-function mutations of residues within the catalytic SET domain of EZH2 occur in diffuse large B-cell lymphoma (DLBCL) and follicular lymphoma, and result in enhanced H3K27 trimethylation and transcriptional repression." (PMID 28445158, 2017). "The histone methyltransferase EZH2 has an essential role in the development of follicular lymphoma (FL)." (PMID 28430172, 2017). "Recurrent mutations at Y641 and A677 have been shown to increase the trimethylase activity of EZH2 and drive the development of diffuse large B-cell and follicular lymphoma." (PMID 24367611, 2013). "Mutations in EZH2 (Y646) and CD79B (Y196) were detected in 13.2% and 8% of the samples, respectively, almost exclusively in follicular lymphomas and diffuse large B-cell lymphomas." (PMID 23361872, 2013). "Importantly, inhibition of EZH2 is currently used in the treatment for other malignancies, including follicular lymphoma; and in MM it can lead to re-expression of CD38." (PMID 38493239, 2024). "The alterations of EZH2 and PRC2 are frequently associated with a wide variety of human cancers, including hematopoietic malignancies, and the EZH2 inhibitor, tazemetostat, has been approved for the treatment of follicular lymphoma." (PMID 38346162, 2024). "Respectively 7.2% and 21.7% of the cases of follicular lymphoma and DLBCL had “gain-of-function” point mutations that caused a transition from tyrosine to histidine in codon 641 (Tyr641) in the catalytically active SET domain of the EZH2 protein." (PMID 37830606, 2023). "An EZH2 inhibitor (PF-06821497) developed by Pfizer has entered phase 1 testing in patients with small cell lung cancer, castration-resistant prostate cancer, and follicular lymphoma (NCT03460977)." (PMID 36076977, 2022). "Currently, EZH2 (Enhancer of Zeste Homolog 2) inhibitors (EZH2i) are being tested in the clinic in multiple cancer indications, and this targeted cancer therapy is approved for use in epithelioid sarcoma and relapsed/refractory follicular lymphoma." (PMID 34925340, 2021). "The research found that EZH2 mutations, which cause the change in a single tyrosine in the SET domain of the EZH2 protein (Tyr641), have a high mutation rate in follicular lymphoma (FL), and these mutations were very stable during the development of the disease." (PMID 34604069, 2021). "Mutations in EZH2 are prevalent in certain B-cell lymphoma subtypes such as diffuse large cell lymphoma and follicular lymphoma; while no EZH2 mutation has been reported in the mantle cell lymphoma (MCL)." (PMID 32850364, 2020). "The dysregulation of H3K27 trimethylation (H3K27me3) is important in human tumorigenesis, and some reports have shown that mutant EZH2 increases the level of H3K27me3 in follicular lymphoma, germinal center B-cell type diffuse large B-cell lymphomas and metastatic skin melanoma." (PMID 30984620, 2019). "Epigenetic mechanisms appear to be involved in the overexpression of EZH2 in MM, rather than the gain-of-function mutation observed in follicular lymphoma." (PMID 30555699, 2018).
follicular lymphoma (continued). "Follicular lymphoma (FL) and germinal-centre B-cell like (GCB) diffuse large B-cell lymphoma (DLBCL) in particular were found to frequently harbour EZH2 gain-of-function mutations that renders them particularly sensitive to EZH2 inhibition." (PMID 30555699, 2018). "EZH2 seems to have an active role in lymphoid malignancies since EZH2 gain-of-function mutations have been identified in germinal center B cell diffuse large-cell B cell lymphomas (DLBCL) and follicular lymphomas." (PMID 27793053, 2016). "Additionally, gain-of-function point mutations at Y641 of EZH2 were identified in 22% of DLBCL and 7-12% of follicular lymphomas." (PMID 27449082, 2016). "This mutation mediates gain-of-function of EZH2 enzymatic activity leading to increased levels of trimethylated H3K27 (H3K27me3) and resulting in down-regulation of Polycomb target genes such as TCF4, FOXP1, TCL1A, BIK, and RASSF6P in follicular lymphomas." (PMID 27793053, 2016). "Heterozygous point mutations of EZH2 occurring at tyrosine 641 (Y641) within the C-terminal catalytic SET domain of EZH2 are observed in 22% of germinal center B-cell (GCB) diffuse large B-cell lymphomas (DLBCL) and 7%—12% of follicular lymphomas (FL), and contribute to EZH2’s oncogenic potential." (PMID 39769907, 2024). "Notably, both inhibitors reduced the growth of EZH2 GOF mutant follicular lymphoma." (PMID 36105358, 2022). "To date, tazemetostat is the only EZH2 inhibitor approved by the FDA for epithelioid sarcoma and follicular lymphoma." (PMID 41601922, 2026). "Several EZH2 inhibitors have been developed, including tazemetostat (EPZ-6438), which has received FDA approval for the treatment of follicular lymphoma and epithelioid sarcoma." (PMID 41226368, 2025). "In 2020, tazemetostat, a selective EZH2 inhibitor, was approved by the US Food and Drug Administration (FDA) to treat patients with epithelioid sarcoma and refractory follicular lymphoma." (PMID 38339397, 2024). "These ideas have led to considerable efforts focused on developing efficient and selective epigenetic inhibitors, including one EZH2 inhibitor, tazemetostat (EPZ-6438), which is FDA-approved for follicular lymphoma and epithelioid sarcoma." (PMID 39796709, 2024). "Recent studies have suggested that EZH2 is a potential target in DMG, substantiated by the recent FDA approval of Tazemetostat (TazverikTM, Epizyme) for epithelioid sarcoma and follicular lymphoma." (PMID 35395831, 2022). "EPZ6438 (tazemetostat), an EZH2 inhibitor, is an FDA-approved drug for epithelioid sarcoma and follicular lymphoma in 2020." (PMID 36276954, 2022). "Currently, phase II trials are ongoing in EZH2-mutant DLBCL, as Tazemetostat was recently approved by the FDA for R/R EZH2-mutant follicular lymphoma." (PMID 35326604, 2022). "The EZH2 inhibitor, tazemetostat has recently been approved by the FDA for the treatment of follicular lymphoma and its efficacy for DLBCL is being studied." (PMID 33513156, 2021). "Tazemetostat, a selective inhibitor of EZH2, was the first compound of this class that was approved by the FDA for the treatment of locally advanced epitheloid sarcoma and follicular lymphoma in 2020." (PMID 33371192, 2020). "In a phase II trial for follicular lymphoma (FL), the experimental group with EZH2 mutations showed a higher ORR and progression-free survival (PFS) compared to the control group without EZH2 mutations." (PMID 40299416, 2025). "Recurrent mutations of genes involved in epigenetic regulation (e.g. KMT2D, CREBBP, and EZH2), JAK-STAT pathway (e.g. SOCS1, STAT6), immune signaling (i.e. TNFRSF14), and BCR/NFKB signaling (e.g. CARD11, CD79B) were previously reported in follicular lymphoma cases." (PMID 35795062, 2022). "In contrast to systemic follicular lymphoma and the GC subtype of DLBCL, no recurrent EZH2 somatic mutation was found in our PCFCL, LC cases, in accordance with its rarity in PCFCL." (PMID 35452489, 2022).
follicular lymphoma (continued). "Also, small-molecule compounds that interfere with the EED/EZH2 interaction have been developed (e.g., astemizole and DC-PRC2in-01) and tested in PRC2-dependent follicular lymphomas." (PMID 36105358, 2022). "To date, multiple inhibitors targeting EZH2 have been reported, of which Tazemetostat was approved by the Food and Drug Administration (FDA) in January 2020 for the treatment of advanced epithelioid sarcoma and follicular lymphoma." (PMID 36076977, 2022). "Tazemetostat is a selective, reversible, small-molecule inhibitor of EZH2 that has been used in clinical trials for refractory non-Hodgkin’s B-cell lymphoma, diffuse large B-cell lymphoma, follicular lymphoma, and advanced epithelioid sarcoma." (PMID 35008848, 2021). "Finally, in 2020, the FDA granted the accelerated approval to tazemetostat, a first-in-class inhibitor of the epigenetic writer “enhancer of zeste homolog 2” (EZH2), for the treatment of epithelioid sarcoma and relapsed/refractory follicular lymphoma." (PMID 34930302, 2021). "Moreover, genetic and pharmacological inhibition of the methyltransferase EZH2 controls SESN1 expression and its subsequent activity on mTORC1 in follicular lymphoma." (PMID 31546746, 2019). "Recently, three EZH2 inhibitors have been observed in clinical trials including CPI-1205 in B-Cell Lymphomas, E7438 in Advanced Solid Tumors/B Cell Lymphomas and GSK2816126 in Relapsed/ Refractory Diffuse Large B Cell and Transformed Follicular Lymphomas." (PMID 29100322, 2017). "Several recent studies have shown that heterozygous point mutations affecting tyrosine 641 (Y641) within the C-terminal catalytic SET domain of EZH2 have been identified in 22% of germinal center B cell diffuse large-cell B cell lymphomas (DLBCL) and in 7-12% of follicular lymphomas." (PMID 27793053, 2016). "Several specific inhibitors of EZH2, which catalyzes tri-methylation of histone H3 at Lys 27 (H3K27me3), have been developed, and Tazemetostat has been approved by the FDA for epithelioid sarcoma, diffuse large B-cell lymphoma and relapsed or refractory follicular lymphoma." (PMID 39455556, 2024). "However, other studies have not found a correlation between EZH2 mutation and loss of in vitro H3K27 trimethylation in follicular lymphoma." (PMID 24367637, 2013).